INS (insulin)
Diseases named in the same sentence as INS in open-access papers (continued):
Sharing a sentence is not in itself a finding about the gene and the disease.
diabetes (continued). "Targeting dipeptidyl peptidase-IV (DPP-IV) inhibition in diabetes leads to improvement of impaired insulin secretion, reduction of glucagon, and eventually lowering of bloodstream glucose." (PMID 33670795, 2021). "In contrast, the two groups had similar rates of diabetes, hypertension, history of cardiovascular diseases, previous cancer, urinary catheter use, and glucose and insulin levels." (PMID 33815869, 2021). "For the diabetic group it was also included: type of diabetes, body mass index and use of metformin therapy prior to hospitalization and the in-hospital medications metformin, insulin and dexamethasone/prednisolone (both in the same variable)." (PMID 34256824, 2021). "Eventually, in some individuals who are genetically predisposed to develop T2D, pancreatic β-cells are unable to maintain the increased demand for insulin, and overt diabetes ensues." (PMID 34673835, 2021). "Pioglitazone is an insulin sensitizer used for controlling the serum glucose of type 2 diabetes mellitus." (PMID 34371651, 2021). "Of the total sample of 52,443 individuals, 7.5% (95% CI 7.0; 7.8) reported having diabetes; of these, 84.0% were using oral diabetes medications, and 20.4% were using insulin." (PMID 34182965, 2021). "In the context of self-care, adolescents with diabetes need to perform capillary blood glucose testings, take insulin injections or use an insulin pump, all of them procedures that often have certain impact on both self-esteem and self-image." (PMID 33672506, 2021). "Hepatic insulin clearance is suppressed in individuals with diabetes and is related to the severity of metabolic syndrome." (PMID 34992579, 2021). "The purpose of the study was to quantify the relationship of acuteglucose and insulin postprandial responses with longer-term effects on diabetes-relatedrisk factors by performing a systematic review and meta-analysis of dietary interventionstudies." (PMID 32277270, 2021). "First, the study population included only Japanese patients whose duration of diabetes was relatively long, and the proportion of patients on insulin was high." (PMID 33907279, 2021). "As one of the most extensively studied metabolites, SCFAs affect glucose metabolism and insulin sensitivity by participating in a variety of pathways, thereby affecting the development of diabetes." (PMID 34447287, 2021). "Mice with targeted global disruption of the GHR gene (GHRKO mice) are excellent models of LS, presenting an obese, growth-retarded phenotype with low levels of IGF-1 and insulin, high levels of GH, and enhanced resistance to diabetes and cancer." (PMID 33774052, 2021). "Diabetes mellitus is characterized by chronic hyperglycemia resulting from inadequate secretion or inefficient utilization of insulin." (PMID 34564163, 2021). "Compared to the primary or even secondary care level, inpatients were treated more often with insulin, had higher HbA1c levels and more diabetes-related problems, etc.." (PMID 33836823, 2021). "FXR activation has also, however, been shown in animal models to reduce the signs of diabetes through increased insulin production from pancreatic β-cells and subsequent glucose regulation." (PMID 34452145, 2021). "Muscle, one of the major targets of insulin, is one of the first tissues to develop insulin resistance in a state of general obesity, diabetes, and other forms of disorders of glucose metabolism." (PMID 35392577, 2021). "Regarding diabetes-related factors, most of Cluster 4 members had diabetes (89.29%), they had the highest levels of fasting blood glucose (m = 149.50 mg/dl), insulin levels (m = 16.05 μIU/ml) and insulin resistance (HOMA-IR, m = 6.54)." (PMID 34362963, 2021). "Current developments in the world of cell encapsulation in terms of diabetes mellitus have indicated the potential of stem cell-derived insulin-producing cells; for example, insulin-producing β cells from patient-induced pluripotent stem cells (iPSCs)." (PMID 34940547, 2021).
diabetes (continued). "Diabetes mellitus is chronic metabolic trouble marked by a high blood sugar level due to abnormal insulin synthesis or action." (PMID 33802826, 2021). "One participant with diabetes claimed that he had been advised on insulin adjustment by the doctor in the past years." (PMID 33530941, 2021). "Diabetes mellitus (DM) is a serious, chronic disease that is characterized by high blood glucose levels, resulting in aberrant insulin production and lower sensitivity of acceptor cells of this hormone." (PMID 33478014, 2021). "The groups of patients with T1DM were similar in diabetes duration, HbA1c, daily insulin requirement, lipid parameters, and thyroid hormones." (PMID 34439776, 2021). "In diabetes, injections of insulin increase epinephrine levels and blood monocytes, and presumably as a consequence thereof, patients with type 2 diabetes exhibit high levels of blood monocytes, although hyperglycemia also contributes to this effect." (PMID 34091064, 2021). "Inability of β-cells to secrete the appropriate amount of insulin to cover the organism’s needs leads to diabetes mellitus." (PMID 33888791, 2021). "Obesity, through an inappropriate lifestyle in combination with genetic factors leads to insulin resistance, β cell stress, dysfunction of β cell and a progressive decline in insulin secretion, which eventually leads to diabetes." (PMID 34039404, 2021). "To study the response of insulin-treated zebrafish larvae to anti-diabetes drugs, we evaluated the pancreatic islet with pioglitazone (PIO) treatment." (PMID 34358068, 2021). "The changes in salivary amylase depends on the type of diabetes, the type of insulin treatment or the quality of glycemic control." (PMID 33800850, 2021). "Patients with diabetes have accelerated muscle catabolism because of insulin signal attenuation and insulin resistance." (PMID 33920957, 2021). "Type 2 diabetes, which is non‐insulin dependent, accounts for ≃90–95 per cent of the incidence of diabetes within the human population." (PMID 33780148, 2021). "FPG is one of the most commonly used indicators for diabetes, as it reflects beta cell function and generally indicates the secretion of basal insulin." (PMID 34489862, 2021). "In rat or mouse models, STZ given intravenously or intraperitoneally induces destruction of insulin-secreting β cells and eventually leads to diabetes." (PMID 33959665, 2021). "Patients with diabetes were on reasonably good metabolic control as testified by HbA1c levels, and a significant proportion of them was on insulin treatment." (PMID 34271920, 2021). "In the group with diabetes, metformin and insulin were used by 62.2% and 30.7% of patients, respectively." (PMID 33506050, 2021). "Maturity‐onset diabetes of the young (MODY) is a group of rare monogenic diabetes (1–2%), genetically determined, resulting in changes in the functioning of insulin secretion of pancreatic beta cells." (PMID 34019234, 2021). "Medical history included insulin-treated type 2 diabetes mellitus complicated by severe peripheral polyneuropathy and chronic kidney disease." (PMID 33492465, 2021). "Metformin is a synthetic biguanide, orally effective and insulin sensitizing anti-diabetic drug, which for most patients is the first line anti-hyperglycemic for the treatment of type 2 diabetes mellitus (T2DM)." (PMID 34421827, 2021). "Potassium ion concentrations modulate calcium influx and insulin secretion in beta cells, and in disruption of ion channel function leads to impaired glucose-induced insulin secretion and diabetes." (PMID 33983929, 2021). "For individuals with diabetes, regular shots of insulin are required to maintain normal blood glucose levels." (PMID 33466845, 2021). "The prediction of diabetes and pre-diabetes can further be refined by addition of fasting and, in particular, postprandial insulin measurements." (PMID 33859227, 2021).
diabetes (continued). "MAPKs play a role in the phosphorylation of serine 636/639 of IRS1 resulting in the defective activation of the PI3K by insulin in cells from patients with diabetes." (PMID 33708999, 2021). "In insulin-producing β-cells, pro-inflammatory cytokine-mediated inflammation is contributing to cell death, eventually leading to the onset and progression of diabetes." (PMID 34360779, 2021). "Diabetes mellitus is a metabolic disorder characterized by chronic hyperglycemia resulting from impaired insulin secretion or insulin resistance." (PMID 34899946, 2021). "The progression toward impaired glucose tolerance and frank diabetes is totally accounted for by impaired insulin secretion." (PMID 33555509, 2021). "Initial optimization of insulin therapy allowed for better diabetes control, normalization of liver size and some catch-up growth; however, her height remained under familial target." (PMID 34419042, 2021). "Non-insulin dependent diabetes mellitus (NIDDM) or type 2 diabetes is caused; due to insufficient insulin secretion via dysfunctional pancreatic β-cell, or insulin dysfunction due to decreased insulin sensitivity." (PMID 33879744, 2021). "Pancreas-specific Bmal1 knockout (KO) mice develop diabetes due to impaired insulin secretion because the circadian clock in pancreatic β cells plays a role in insulin exocytosis." (PMID 33676029, 2021). "Insulin is a peptide hormone with many physiological functions, besides its use in diabetes treatment." (PMID 33920964, 2021). "Among anti-diabetes drugs used for management, insulin (41.3%) was the most frequently involved in DTPs followed by the combination of metformin and insulin (32.1%)." (PMID 34077431, 2021). "Diabetes mellitus (DM) is a chronic disease in which the body exhibits compromised capability to produce or respond to insulin, leading to abnormal metabolism of carbohydrates and elevated levels of blood glucose." (PMID 34659110, 2021). "Additional analysis is necessary to determine the effect of insulin treatment on outcomes in COVID‐19 patients and the interaction with previous diabetes diagnoses and hyperglycaemia." (PMID 34505406, 2021). "BlueStar (Welldoc, Columbia, MD), first to receive US FDA clearance for diabetes mellitus management, comes with an app which requires a physician prescription and enables patients to titrate insulin dosing by using the proprietary insulin calculator." (PMID 33513268, 2021). "In rats with streptozotocin-induced diabetes, the administration of a subcutaneous injection of insulin showed a fast decrease in the glycemia, reaching the lowest values at around 2–3 h post-administration." (PMID 35056935, 2021). "In any case, these compensatory processes are transient, while following a hyperinsulinemic lifestyle, in the long run, increases insulin resistance and beta-cell depletion, leading to progressive destruction and the development of diabetes." (PMID 33985566, 2021). "OS and the chronic inflammatory process contribute to the development of IR and insulin secretion dysfunction, leading to the development of prediabetes and diabetes." (PMID 35052583, 2021). "In metabolic diseases like diabetes mellitus, insulin signaling is disturbed, leading to an impaired glucose homeostasis." (PMID 33919975, 2021). "This process is essential for the utilization of glucose in peripheral tissues as islet dysregulation is a principal contributing factor in diabetes disease progression, resulting in mismatched insulin secretion and peripheral insulin sensitivity." (PMID 34045505, 2021). "Diabetes simulators are platforms that are used to emulate certain physiological characteristics of a diabetic patient and allow the user to perform experiments by controlling different parameters related to insulin dosing strategies for diabetes patients." (PMID 33466659, 2021). "From 4124 patients with type 1 diabetes mellitus older than 18 years receiving insulin analogues from SES-RS, we selected 566 potential participants." (PMID 33905628, 2021).
diabetes (continued). "In this regard, it has been observed that hypomorphic heterozygous mice (PREP1i/+), expressing low levels of PREP1 protein, are protected from streptozotocin-induced diabetes, exhibit improved insulin sensitivity, and reduce visceral adipose tissues." (PMID 34327205, 2021). "Since LPL is upregulated by insulin, any state of insulin resistance or diabetes mellitus will result in diminished LPL activity, elevated TG lipoproteins, and reduced HDL." (PMID 34299261, 2021). "Diet control, reasonable exercise, oral antidiabetic drugs, and insulin injection are routine options for the prevention and treatment of diabetes." (PMID 34447287, 2021). "Diabetes is one of the common chronic diseases, which is related to decreased insulin secretion and weakened or disappeared insulin action." (PMID 34476007, 2021). "Of the 21 women with diabetes, seven had insulin-controlled PGDM, and 14 had GDM treated by metformin." (PMID 33803995, 2021). "LFS is calculated from variables including serum aspartate transaminase/alanine transaminase (AST/ALT) ratio, fasting serum aspartate transaminase (AST) level, fasting serum insulin level, presence of metabolic syndrome and diabetes mellitus." (PMID 34184611, 2021). "In mRNA expression levels in isolated islets, insulin and its transcriptional factors such as Pdx-1 and MafA were significantly increased in combination therapy in an early phase of diabetes." (PMID 34373487, 2021). "Imidazole propionate blocks insulin conduction through the mTORC1 signaling pathway and then induces diabetes." (PMID 34447287, 2021). "Serum from animals subjected to diabetes and fasting exhibit distinctive profiles, despite the fact both conditions are characterized by low serum insulin concentrations and both conditions ultimately induce skeletal muscle and fat breakdown." (PMID 33915127, 2021). "The organisation of diabetes management within the healthcare system also affects patient access to insulin." (PMID 33483763, 2021). "Various theories have been reported to identify the reasons behind the disturbance in glucose homeostasis resulting in increased blood glucose, insulin level, and HbA1c, and consequently the development of diabetes." (PMID 34778345, 2021). "For example, people with diabetes in New Zealand do have access to free and/or highly subsidised insulin, hypoglycaemic agents, glucose strips, etc., though this does require a visit to a general practitioner and a minimal prescription charge." (PMID 34136579, 2021). "The majority of women with pre-existing diabetes were receiving insulin prior to ANC administration." (PMID 33600450, 2021). "In 2018, the insulin sale was worth S21.3 billion globally and accounted for 43.7% of the diabetes drug market." (PMID 33802091, 2021). "All synthetic insulin analogs have their individual and specific pharmacokinetic profile, which facilitates their usage as therapeutic agents to treat diabetes mellitus (DM)." (PMID 34065812, 2021). "Warfarin and insulin are the only medications he ever refers to by name—the others he knows by condition (diabetes, blood pressure), shape and size (the ‘big one’), time of day (the ‘night one’, or organ (‘heart’)." (PMID 34446490, 2021). "Resistance exercise training appears to be a promising intervention to improve the health of those living with insulin treated diabetes, particularly those who are older." (PMID 34880011, 2021). "Hyperglycemia, a common trait shared in both Type 1 (insulin dependent) and Type 2 (non-insulin dependent) diabetes mellitus, resulting from impaired insulin signaling, is one of the major etiologies for cardiovascular complications in diabetic patients." (PMID 34065781, 2021). "Current treatments for diabetes include hyperglycemic drugs such as oral hypoglycemic agents, insulin, exercise therapy, and surgery." (PMID 35185787, 2021). "T2DM patients considered insulin as the last means to treat diabetes and expressed fear of painful injections, which affects adherence." (PMID 33651277, 2021).
diabetes (continued). "Diabetes mellitus (DM) is a chronic metabolic disease and characterized by hyperglycemia that result from defects in insulin secretion, insulin action, or both." (PMID 34504407, 2021). "Compared to the strictest glucose controlled category of controls, approximately 60% decline was observed in β-cell compensation and insulin sensitivity, in impaired glucose tolerant offspring of subjects with type-2 diabetes mellitus." (PMID 34017668, 2021). "Insulin therapeutic inertia was more likely among those with shorter diabetes duration (adjusted OR 0.9, 95% CI 0.87, 0.98)." (PMID 34116645, 2021). "Previous studies using mammalian type 1 diabetes models that chronic ER stress in insulin-producing cells resulted in the onset and pathogenesis of diabetes." (PMID 34769468, 2021). "Diabetes mellitus (DM) is a metabolic disease characterized by the persistent state of hyperglycemia due to increased insulin resistance and/or decreased pancreas beta cells function." (PMID 34760944, 2021). "In Family 1, two male siblings presented with diabetes at the ages of 16 and 12 years, respectively, requiring insulin replacement therapy." (PMID 34373539, 2021). "In particular, the effects of vitamin D on diabetes include improvement of insulin sensitivity (e.g., through modulation of adiponectin gene), increase of insulin gene transcription, insulin receptor expression, and glucose transport." (PMID 34603080, 2021). "Regarding diabetes medication, the majority were on oral antidiabetic therapy (66.2%), 11.7% of patients were treated with insulin, 2.1% with only diet and the rest (20%) were on combined therapy (oral + insulin)." (PMID 34332613, 2021). "To further investigate the functional implication of the histological changes in the endocrine pancreas of diabetic Prlr-/- mice, we determined the pancreatic expression and circulating levels of insulin and glucagon 11 weeks after inducing diabetes with STZ." (PMID 33746901, 2021). "Currently, the main treatments for diabetes include insulin injection, oral diabetes medications, and pancreatic islet transplantation." (PMID 34690773, 2021). "It has previously been reported that the potential of GNPs as a carrier of trans-mucosal insulin delivery in the treatment of diabetes mellitus leads to improved pharmacodynamic activity." (PMID 34572503, 2021). "Current treatments for diabetes predominantly rely on oral anti-hyperglycaemic agents or the subcutaneous administration of insulin to patients." (PMID 34452145, 2021). "Due to the nature of this type of diabetes, oral and intravenous glucose tolerance tests are prohibited, and the gold standard in diagnosing insulin sensitivity remains the hyperinsulinemic-euglycemic clamp, which is difficult and time-consuming." (PMID 34822453, 2021). "Before the advent of insulin in 1921, carbohydrate- and calorie-restriction diets were used to manage diabetes." (PMID 34371888, 2021). "The covariates this study will adjust are age, sex, living alone, duration of diabetes, hypoglycemic episodes in the last year, and duration of insulin use." (PMID 34744863, 2021). "Insulin pumps have become more user-friendly, compact and reliable resulting in increased popularity among people with diabetes, particularly in the paediatric T1D population." (PMID 33950566, 2021). "We also observed that metformin, glibenclamide, and insulin were among the common hypoglycemic medications that were used for the management of diabetes." (PMID 35199748, 2021). "Other specific types of diabetes also exist such as genetic abnormalities of β-cell, genetic defects in the action of insulin, diseases of the exocrine pancreas or endocrinopathies." (PMID 34574159, 2021). "Currently, there are various therapies available to control diabetes, such as insulin, pharmaco and diet therapy." (PMID 34065175, 2021).